ZBED11 (zinc finger BED-type containing 11)
Synonyms: FAM200B; C4orf53
Tractability: No criterion of Open Targets' tractability assessment is met for any kind of drug.
Gene: Protein-coding gene on chromosome 4 (15,681,506 to 15,690,447, forward strand). Ensembl gene ENSG00000237765.
Genetic constraint (gnomAD): Loss-of-function variants: 42 observed, 46.91 expected, observed/expected ratio (o/e) 0.9, 90% interval 0.7 to 1.16. The upper end of that interval is the gene's LOEUF score, 1.16, which puts it in group 5 of 6, group 1 being the genes least tolerant of losing a copy. Missense variants: 703 observed, 742.74 expected, observed/expected ratio (o/e) 0.95, 90% interval 0.89 to 1.01. Synonymous variants: 229 observed, 263.34 expected, observed/expected ratio (o/e) 0.87, 90% interval 0.78 to 0.97.
Homologues: Orthologues: chimpanzee FAM200B (99% identical), dog FAM200B (91% identical). Paralogues in human: ZBED8L (66% identical), SCAND3 (35% identical), ZBED5 (31% identical), ZBED8 (28% identical), EPM2AIP1 (18% identical), THAP12 (14% identical), ZMYM4 (12% identical), ZMYM3 (10% identical), ZMYM6 (10% identical), ZMYM2 (9% identical), GTF2IRD1 (8% identical), ZMYM1 (8% identical), and 6 more.